HEY2 (hes related family bHLH transcription factor with YRPW motif 2)
Diseases named in the same sentence as HEY2 in open-access papers (continued):
Sharing a sentence is not in itself a finding about the gene and the disease.
infection (5 papers, 2015 to 2025). The state of being infected such as from the introduction of a foreign agent such as serum, vaccine, antigenic substance or organism. "HEY2 protein levels were reduced by 50% 48 h afterthe infection of MDA MB 231 cells with virus expressingshRNA against RBPjk." (PMID 30930637, 2019). "In both, Notch signaling was successfully activated upon infection with NICD virus as demonstrated by significant increase in Notch target gene HEY2 mRNA." (PMID 26161746, 2015). "Infection with Ad-CMV-Cre resulted in the deletion of Rbpj and the loss of the stimulatory effect of the NOTCH2 gain-of-function on the Notch target genes Hes1, Hey1, and Hey2 (not shown) since RBPJκ is required for their induction by Notch." (PMID 37865314, 2023). "Ad-CMV-Cre, but not Ad-CMV-GFP, infection led to the inversion of the conditional by inversion (COIN) module and expression of the Notch2ΔPEST or Notch2ΔINV mRNA with the consequent induction of Hes1, Hey1, and Hey2 demonstrating activation of Notch signaling." (PMID 37865314, 2023).
adenocarcinoma (1 paper, 2015). A common cancer characterized by the presence of malignant glandular cells. "However, we could not observe such an induction of Hey1, Hey2 or Id2 in primary human vascular smooth muscle cells from the umbilical artery, HEK293, HeLa or A549 adenocarcinoma cells.This indicates that endothelial cells react much stronger to BMPs in the serum than other cell types and cell lines." (PMID 25799559, 2015).
HEY2 also shares sentences with these, for which no sentence is quoted: astrocytoma (2 papers); atrioventricular septal defect (2); COVID-19 (2); heart disease (2); heart failure (2); hypertrophy (2); liver fibrosis (2); non-small and small cell lung cancer (2); pancreatic ductal adenocarcinoma (2); tricuspid atresia (2); Ventricular arrhythmia (2); aortic coarctation (1); arteriovenous malformations (1); atrial septal defect (1); brain tumors (1); cardiac arrhythmia (1); chronic apical periodontitis (1); cyst (1); dilated cardiomyopathy (1); endometriosis (1); familial atrial fibrillation (1); glomerular disease (1); glomerulosclerosis (1); heart rhythm disease (1); hypertrophic cardiomyopathy (1); lung adenocarcinoma (1); Neurodevelopmental delay (1); preeclampsia (1); pulmonary stenosis (1); ventricular septal defect (1).